CLOCK (clock circadian regulator)
Diseases named in the same sentence as CLOCK in open-access papers (continued):
Sharing a sentence is not in itself a finding about the gene and the disease.
breast carcinoma (56 papers, 2013 to 2025). "The results indicated that high expression levels of OPN4, NOS2, GPR157, NCOA2, CLOCK, and TH were associated with shorter OS in breast cancer patients, while high expression of EGR3, NR1H3, RELB, SIAH2, and ADRB1 was linked to improved survival rates." (PMID 41031266, 2025). "Within the group of women with breast cancer who had one of these SNPs, there was also a significant correlation with the rs11932595 mutation in CLOCK." (PMID 39463009, 2024). "Upon examining the primary impacts of each single nucleotide polymorphism (SNP), variations in CLOCK rs11133373 were associated with an increased risk of breast cancer." (PMID 39525867, 2024). "We observed some indication that methylation of multiple CpGs in CRY1 and CLOCK was inversely associated with breast cancer." (PMID 39587706, 2024). "Two studies demonstrated a link between hypermethylation of the CLOCK gene with lower breast cancer risk which is congruent with our findings." (PMID 39587706, 2024). "Nevertheless, in CRY1 CpG2 and CpG5 and in CLOCK CpG1 increasing levels of methylation tended to be associated with lower odds of breast cancer (OR 0.88; 95% CI 0.76–1.02, OR 0.84; 95% CI 0.74–0.96, and OR 0.80; 95% CI: 0.68–0.94, respectively)." (PMID 39587706, 2024). "To provide insight into the relationship between CLOCK polymorphisms and breast cancer risk, we performed a meta-analysis among 10,164 participants, including 5488 breast cancer cases and 4676 controls." (PMID 37036639, 2023). "We found that the mutation types of one CLOCK SNP, rs3749474 were significantly associated with the risk of breast cancer." (PMID 37036639, 2023). "The mutation types of CLOCK gene rs3749474 are negatively associated with the risk of breast cancer." (PMID 37036639, 2023). "PubMed, Cochrane Library, and Embase databases were electronically searched to collect studies on the association between CLOCK gene polymorphisms and breast cancer risk from inception to February 14, 2022." (PMID 37036639, 2023). "In this study, we conducted a meta-analysis to systematically evaluate the associations between CLOCK gene polymorphisms and breast cancer risk." (PMID 37036639, 2023). "This study performed a meta-analysis of the association between CLOCK gene polymorphisms and breast cancer risk." (PMID 37036639, 2023). "Single nucleotide polymorphisms in the Cryptochrome Circadian Regulator 2 (CRY2) and CLOCK genes have also been shown to increase the risk of breast cancer." (PMID 36661673, 2022). "Loss of CLOCK gene, a transcription factor important in the regulation of circadian rhythm, has been associated with tumor progression in breast cancer." (PMID 35200555, 2022). "As a result, expression of BMAL1 and CLOCK was associated with poor prognoses in breast cancer patients." (PMID 32316196, 2020). "This circadian–cancer connection was later confirmed by other authors, who showed genetic associations between the circadian genes NPAS2, CRY2 and CLOCK and breast cancer risk." (PMID 33419321, 2020). "In these workers with the rs8150 polymorphism from AANAT gene, as well as for the rs10462028 polymorphism from the CLOCK gene, was observed an increased frequency of breast cancer, while a lower risk was observed for the rs3816358 from ARNTL gene." (PMID 30873119, 2019). "Concerning CLOCK gene, it was found that carrier subjects CT and CT+TT genotypes exhibited an increased risk of breast cancer in comparison to CC carriers." (PMID 30873119, 2019). "The use of estrogen hormone also had an association with CLOCK gene expression and development of breast cancer and in colorectal cancer, increased expression of CLOCK has been reported in tumor tissue compared to healthy adjacent tissues." (PMID 31151182, 2019). "Previous studies reported significant associations between variants of different loci in the CLOCK gene and breast cancer." (PMID 31358835, 2019).
breast carcinoma (continued). "A possible explanation for the association between variants in the CLOCK gene and breast cancer risk would be that hypermethylation of the CLOCK promoter reduces the risk of breast cancer." (PMID 31358835, 2019). "Hoffman and Colleagues in one of the studies included in this analysis address this issue finding that hypermethylation in CLOCK gene promoter reduces the risk of breast cancer." (PMID 28177907, 2017). "In the human population, CLOCK variants have been found to be associated with breast cancer risk, and CLOCK promoter hyper methylation will reduce breast cancer risk." (PMID 28580187, 2017). "Hypermethylation of the Clock promoter reduces breast cancer risk, with lower levels of CLOCK in healthy controls." (PMID 27590298, 2016). "The overexpression of CLOCK has been linked to increased proliferation in luminal breast cancer cells." (PMID 26220712, 2015). "Numerous single nucleotide polymorphisms (SNPs) in the CLOCK gene have also been correlated with increased breast cancer risk." (PMID 26220712, 2015). "In the main effects analysis, two SNPs in BMAL1 and CLOCK were associated with risk of breast cancer." (PMID 23822714, 2013). "In subjects with three consecutive night shifts, the odds of reduced risk of breast cancer associated with carriage of variant alleles of SNPs in CLOCK (rs3749474), ROR-b (rs3903529, rs3750420) and MTNR1A (rs131113549) were found noteworthy." (PMID 23822714, 2013). "The carriers of variant TT genotype of SNP rs2278749 in the BMAL1 gene with an OR of 0.45 (95% CI, 0.23- 0.90) and the homozygote genotype TT of rs3749474 in the CLOCK gene with an OR of 0.64 (95% CI, 0.45- 0.92) had reduced risk of breast cancer." (PMID 23822714, 2013). "In CRY1 CpG2 and CpG5 and in CLOCK CpG1, increasing levels of methylation tended to be associated with lower odds of breast cancer, with odds ratios (OR) of 0.88 (95% confidence interval (CI) 0.76–1.02), 0.84 (95% CI 0.74–0.96), and 0.80 (95% CI 0.68–0.94), respectively." (PMID 39587706, 2024). "Furthermore, altered expression or function of clock regulatory factors has been implicated in certain types of cancer and specific genetic variations (polymorphisms) in CLOCK genes are also linked with breast cancer." (PMID 39587706, 2024). "Therefore, the need for further systematical research on the effects of CLOCK polymorphisms on breast cancer remains." (PMID 37036639, 2023). "However, research findings on the relationship between polymorphisms in the CLOCK gene and breast cancer risk were inconsistent." (PMID 37036639, 2023). "In analysis of the main effects of each single nucleotide polymorphisms(SNPs), variants in CLOCK rs11133373 was associated with breast cancer risk even after false discovery rate (FDR) correction (Odd Ratios (OR) = 1.38 (95% Confident Interval (CI) 1.14–1.69) in CG and CC compared to GG genotype." (PMID 31358835, 2019). "Intronic rs12505266 of CLOCK was significantly associated with an increased predisposition to breast cancer among recessive homozygous genotypes OR = 1.22 (0.83–1.79), p = 0.057 and at marginal significance under a recessive genetic model OR = 1.38 (0.97–1.96), p = 0.07." (PMID 31739444, 2019). "Furthermore, increased methylation in the promoter region of CLOCK has been associated with decreased breast cancer risk." (PMID 29780357, 2018). "Specifically, aberrant methylation of the circadian genes CLOCK and Cry2 was reported, with shift workers exhibiting CLOCK hypomethylation and Cry2 hypermethylation when compared to day workers, a pattern that has been associated with breast cancer and discussed previously." (PMID 26220712, 2015). "Among the differentially methylated genes was hypermethylation of the promoter for miR-219, a miRNA that has been linked to breast cancer development and has been identified as a potential regulator of circadian duration via the modulation of CLOCK- and BMAL1-dependent Per transcription." (PMID 26220712, 2015).
breast carcinoma (continued). "Polymorphisms in the CLOCK gene might be associated with breast cancer risk." (PMID 37036639, 2023). "A rare polymorphism of the CLOCK gene has been associated with an increased risk for developing breast cancer (OR = 3.53; 95% CI +1.09–11.42), and there was a positive interaction between the presence of this genotype and night shift work on risk for developing breast cancer (p = .02)." (PMID 28865460, 2017). "Studies using the gene set analysis method confirmed an association with ARNTL, CLOCK, and RORA and additionally reported an association with RORB, RORC, CRY, and the overall pathway in relation to breast cancer risk." (PMID 40534841, 2025). "They report a similar downregulation of PER1, PER2, CRY2, and HLF, in breast cancer samples while CLOCK, ARNTL(BMAL1), and BHLHE40 levels remained relatively unchanged." (PMID 38319971, 2024). "More specifically, after silencing the CLOCK gene, the genes primarily involved in breast cancer progression included CCL5, SP100, and BDKRB2." (PMID 39587706, 2024). "The literature is limited on ESR and circadian rhythm; so far it seems there is a link between ESR1-induced CLOCK expression in breast cancer cells." (PMID 36985125, 2023). "In a breast cancer mouse model, CLOCK and BMAL1 in the TME promoted tumorigenesis and metastasis through the upregulation of WNT10A-mediated ALDH3A1 expression in cancer stem cells." (PMID 37524704, 2023). "In the 4T1 mouse model of breast cancer, the CLOCK component has been found to induce regular expression of Wnt family member 10A (Wnt10A) and upregulate the expression of downstream acetaldehyde dehydrogenase 3 (ALDH3A1)." (PMID 36647780, 2023). "We have previously reported that CLOCK SUMOylation stimulates breast cancer cell growth by upregulating the transcriptional activity of estrogen receptor-alpha." (PMID 37024472, 2023). "While in KIRC and breast cancer, upregulation of CLOCK, ARNTL and PER3 promotes TME inflammation via modulating macrophages and neutrophils infiltration, which leads to worse prognosis." (PMID 37183243, 2023). "Our study showed that anemic breast cancer patients with a high number of chemotherapy cycles and those carrying at least one C allele for DRD2 and CLOCK SNPs are at greater risk of exhibiting fatigue." (PMID 34979978, 2022). "In terms of genetic predisposition, logistic regression analyses have linked different CLOCK, CRY1, and PER2 genotypes to breast cancer risk, and several studies have implicated specific single-nucleotide polymorphisms." (PMID 35163264, 2022). "Using these technologies, selective targeting of the CLOCK 3’UTR as a novel treatment strategy for malignant breast cancers is needed in order to therapeutically activate the circadian clock genes in CSCs." (PMID 33890571, 2021). "For example, the transcriptional activity of ERα is upregulated in breast cancer via binding with SUMOylation proteins, such as CLOCK and ZFP282." (PMID 34508066, 2021). "In this study, we demonstrated the negative regulation of ALDH activity by the major circadian component CLOCK in murine breast cancer 4T1 cells." (PMID 33890571, 2021). "We additionally suggest a possibility that CLOCK is also reduced under hypoxia-mediated acidosis and reduced CLOCK promotes breast cancer metastasis." (PMID 32316196, 2020). "One of them is NDUFS3, a potential biomarker to discriminate invasive from normal breast cancer, whose expression is controlled by the CLOCK gene." (PMID 32295075, 2020). "Cancer cells and primary breast cancer tissues were immunostained for the measurement of circadian clock proteins (CLOCK, BMAL1 and PER1) and acetylserotonin methyltransferase (ASMT)." (PMID 33194597, 2020). "Based on our findings, the potential role of CLOCK in breast cancer etiology seems plausible referring to both a main effect of individual SNP and gene-gene effects on breast cancer." (PMID 31358835, 2019).
breast carcinoma (continued). "This case-control study analyzed the associations between breast cancer and polymorphisms in circadian clock genes (ARTNL, CLOCK, CRY2, NPAS, and PER2) and in genes of the melatonin pathway as well (AANAT and MTNR1B)." (PMID 30873119, 2019). "With the cut-off point for P-value at 0.05 using permutation test, three SNPs including rs11133373 and rs3749474 in the CLOCK gene, and rs2119882 in the MTNR1A gene have a statistically significant association with breast cancer." (PMID 31358835, 2019). "For example, lower levels of CLOCK were observed in tumor-unaffected tissues in comparison to the affected tissues, in patients with breast cancers that indicates an aberrant overexpression of CLOCK as a possible early event in carcinogenesis." (PMID 31151182, 2019). "For those who carried the CLOCK rs11133373 CC genotype, increment of CUL1 rs758880 A genotype increased the breast cancer risk (OR = 1.84 [95% CI = 1.13–3.00]), but in GG genotype, it showed decreased associations significantly." (PMID 31358835, 2019). "An alternative study supporting the involvement of the CLOCK gene in the development of breast cancer came from a Bonn (Germany) population of shift workers." (PMID 30873119, 2019). "Our analysis indicates that five SNPs, BMAL1 rs2279287, CLOCK rs12505266, CRY2 rs10838524, PER1 rs2735611, PER2 rs934945, are significantly associated with the breast cancer risk in the Polish association study." (PMID 31739444, 2019). "In this line, polymorphisms affecting CLOCK (rs3805151), CRY1 (rs1056560), CRY2 (rs1401417), and PER2 (rs934945) have been associated to breast cancer risk in a Chinese population." (PMID 30873119, 2019). "After FDR correction, four of these genes were individually significantly associated with disease-free survival, including the steroidogenic enzyme CYP11A; LGR6, a WNT regulator and implicated in breast cancer; and PRR7, a central regulator of CLOCK." (PMID 30120411, 2019). "As much as 74% of examined ER-positive breast cancer tissues had a higher CLOCK expression than ER-negative samples measured by immunohistochemical assay." (PMID 29958276, 2018). "The transcript level was significantly up-regulated in the breast cancer tissue samples in comparison with the adjacent normal tissue samples for CLOCK (β-coefficient 0.219, p = 0.002) and TIMELESS (β-coefficient 0.298, p<0.0001)." (PMID 29958276, 2018). "We confirmed that 8 genes—MAPK14, CLOCK, NF2, HMGA2, CXCL12, E2F1, NOTCH1, and CD24—are associated with breast cancer." (PMID 30013305, 2018). "Breast cancer MCF-7 cell line with overexpression of CLOCK and ER showed higher growth than cell lines transfected with empty vector." (PMID 29958276, 2018). "Changes in promoter methylation in the CLOCK gene were also reported among long-term shift workers, which was consistent with the findings on a low level of the CLOCK methylation in breast cancer patients." (PMID 28594926, 2017). "Breast cancer rates are elevated amongst shift-workers, and breast cancer patients express CLOCK hypomethylation and CRY2 hypermethylation in blood and tumorous breast tissue." (PMID 26252151, 2015). "For example, a pair of studies showed that all the breast cancer types tested had CLOCK-promoter hypomethylation and Cry2-promoter hypermethylation when compared to controls." (PMID 26220712, 2015). "The same study also showed that CLOCK knockdown results in increased expression of various tumour suppressor genes and decreased expression of multiple oncogenes, indicating an oncogenic influence by CLOCK on breast cancer development." (PMID 26220712, 2015). "In this study we demonstrated that CLOCK, similar to other circadian clock genes, is subject to modulation by estrogen in breast cancer cells." (PMID 24789043, 2014). "Taken together, our data suggested that CLOCK is a transcriptional target of ERα, and that the product of this gene can modulate cell proliferation in ERα-positive breast cancer cells." (PMID 24789043, 2014).
breast carcinoma (continued). "The potential relevance of our findings to the biology of breast cancer cells was investigated by looking at the effect of reduced CLOCK expression on cell proliferation." (PMID 24789043, 2014). "Subsequent experiments using ERα-positive human breast cancer cell lines showed that both protein and mRNA levels of CLOCK were up-regulated by E2 and ERα." (PMID 24789043, 2014). "Another breast cancer-associated protein, DEC1, has been shown to repress the transcriptional activity of CLOCK." (PMID 24789043, 2014). "It is worthwhile to note that the present work examined the transcriptional mechanism of CLOCK in ERα-positive breast cancer cells, and tried to determine if a correlation between ERα and CLOCK exists in these cells." (PMID 24789043, 2014). "In the main effects analysis, CC carriers of rs4238989 and GG carriers of rs3760138 in the AANAT gene had increased risk of breast cancer, whereas TT carriers of BMAL1 rs2278749 and TT carriers of CLOCK rs3749474 had reduced risk." (PMID 23822714, 2013). "The key circadian genes, PERIOD 2 (PER2 variant 2), CLOCK, TIMELESS, CRYPTOCHROME 1 (CRY1) and CRYPTOCHROME 2 (CRY2) were all also significantly expressed in all breast cancer cell lines and all patients’ breast cancer tissues examined." (PMID 24683528, 2013). "Aside from utilizing chronotherapy as a therapeutic approach, the group found that the CLOCK level was downregulated in ALDH+ cells in the murine 4T1 breast cancer cells, and overexpression of CLOCK markedly inhibited the tumorigenicity and invasive capacities of these breast cancer cells." (PMID 40869256, 2025). "Polymorphisms in CLOCK, NPAS2, CRY2, RORA, TIMELESS, and ARNTL have been associated with breast cancer." (PMID 40534841, 2025). "The study compiled fifteen epidemiological research papers, five of which focused on shift work employment, and identified BMAL1, BMAL2, CLOCK, neuronal PAS domain protein 2 (NPAS2), CRY1, CRY2, PER1, PER3, and TIMELESS as potential risk variants for breast cancer." (PMID 39525867, 2024). "For instance, a meta‐analysis examining publications with patient samples concluded that there is not a significant correlation between CLOCK SNPs and risk of developing breast cancer." (PMID 39463009, 2024). "BMAL1 and CLOCK, as key transcription factors, are integral to breast cancer progression." (PMID 39139571, 2024). "CLOCK has been identified as a significant modifier of breast cancer incidence." (PMID 37036639, 2023). "The significance of CLOCK in cancer is better understood as it is thought to be a molecular link between disrupted circadian rhythm and cancer, including breast cancer." (PMID 34056582, 2021). "Taken together, miR-182-mediated post-transcriptional regulation of CLOCK may be a novel insight for treatment of breast cancer attenuating tumor malignancy." (PMID 33890571, 2021). "Our findings suggest that increased expression of CLOCK in BCSCs by targeting post-transcriptional regulation overcame stemness-related malignancy and may be a novel strategy for breast cancer treatments." (PMID 33890571, 2021). "The ultimate molecular function of CCNT1 and its interactions with CLOCK and the other predicted genes remains elusive, and any potential role in breast cancer is largely unremarked, as only 3 papers within PubMed mention CCNT1 and breast cancer, and in fact only 39 papers mention CCNT1 and cancer." (PMID 34056582, 2021). "The role of CLOCK in the regulation of ALDH activity in 4T1 mouse breast cancer cells." (PMID 33890571, 2021). "For example, in breast cancer, CLOCK may modulate estrogen receptor-α mediated gene expression using its HAT activity." (PMID 33114365, 2020). "Finally, simultaneous presence of CLOCK CC and PER2 AA genotypes resulted in a higher risk of developing breast cancer." (PMID 30873119, 2019).